SMAD4 (SMAD family member 4)
Diseases named in the same sentence as SMAD4 in open-access papers (continued):
Sharing a sentence is not in itself a finding about the gene and the disease.
tumor (continued). "The synthetic lethality approach has the opportunity to make SMAD4 an actionable target by targeting specifically SMAD4-negative tumor cells, while limiting harm to normal cells." (PMID 37377893, 2023). "In multivariate analyses, high expression of IRS1 in stromal cytoplasm, RUNX3 in tumor nucleus and stromal cytoplasm, and high expression of SMAD4 in tumor and stromal cytoplasm remained independent predictors of improved DSS." (PMID 36900240, 2023). "Other genes that have been studied in rectal cancer with contrasting results include BRAF, PIK3CA, SMAD4, and tumor MSI." (PMID 36900260, 2023). "In early tumorigenesis, the TGF-β/SMAD4 signaling pathway acts as a tumor suppressor, inducing cell cycle arrest and apoptosis." (PMID 36900240, 2023). "In a cohort of PDAC patients, SMAD4/DPC4-negative tumours with high levels of phospho-SMAD2 were more aggressive and had a poorer prognosis." (PMID 37685308, 2023). "These seemingly discrepant observations suggest that the relationship between SMAD4 and tumor immune activity relies on the anatomical structure, histological type, and multiple functions of SMAD4 during different cancer stages." (PMID 37035326, 2023). "We demonstrate that increased expression of RUNX3 and SMAD4 in tumor epithelial and stromal compartments and IRS-1 in stroma are independent predictors of a favorable prognosis in this patient group." (PMID 36900240, 2023). "• SMAD4 gene alterations: SMAD4 gene is a key player in TGF-β signalling which is elevated in basal-like tumours." (PMID 37790705, 2023). "Expression of STING1 and SMAD4 were downregulated in tumour tissues of iCCA, pCCA and dCCA compared to the para‐tumour tissue." (PMID 37488750, 2023). "To check the dependence of tumor cell growth upon the alteration of SMAD4, we restored the tumor suppressor SMAD4 in HT29 and SW620 cell lines." (PMID 37377893, 2023). "These previous studies suggest that SMAD4/DPC4 has a significant tumour suppressive function in the progressive phase of PC." (PMID 37685308, 2023). "Previous studies suggest that SMAD4 acts as a tumor metastatic suppressor in the exquisite context of PTEN-loss mouse models for PCa, whereas TGFβ/SMAD4 activation has also been reported to promote metastatic progression of cancers including PCa." (PMID 37550764, 2023). "Our findings support this canonical notion that SMAD4 expression in the tumor organoids resulted in the suppression of WNT and proliferation, and ChIP-Seq of SMAD4 reveals binding sites at prominent cell cycle genes." (PMID 38136364, 2023). "Similar to organoids grown in 3D culture, DAVID analysis indicated an upregulation in pathways associated with secretory proteins and extracellular regions upon re-expression of SMAD4 in tumor organoids cultured on plastic." (PMID 38136364, 2023). "With the impact of SMAD4 in tumor organoid migratory and invasive capability, it was of interest to understand the transcriptional mechanism of how SMAD4 suppresses this invasive behavior." (PMID 38136364, 2023). "SMAD4 gene expression was compared between normal and tumor colon tissue using the data contained in the UALCAN and TNMplot databases." (PMID 37237640, 2023). "Although SMAD4/DPC4 deficiency in tumour cells enhanced proliferation in vitro, in vivo growth of SMAD4/DPC4-deficient PDAC tumours was significantly inhibited in immunoreactive C57BL/6 (B6) mice." (PMID 37685308, 2023). "SMAD4 loss induces the upregulation of PGK1 in PDAC, which enhances glycolysis and aggressive tumor behavior." (PMID 36807568, 2023). "Genes with SMAD4 binding sites were compared to the significantly up- and downregulated genes from the pINDUCER-SMAD4 tumor organoid RNA-Seq to identify potential direct target genes of SMAD4 activity." (PMID 38136364, 2023). "In this study, we conducted an analysis of STING1 and SMAD4 expression in both CCA tumour tissues and adjacent normal tissues." (PMID 37488750, 2023).
tumor (continued). "SMAD4 is capable of enabling gene transcription and tumor suppression via the TGF-β signaling pathway." (PMID 37049199, 2023). "Briefly, the Smad4 gene was discovered to be a tumor suppressor in pancreatic carcinoma and was later recognized as a critical modulator of TGF signaling." (PMID 38129938, 2023). "The IHC analysis showed successful overexpression of Smad4 in tumor lesions after being treated with nano-lantern, and H&E images showed normal morphology in the mouse parenchyma organs and no metastases in liver or lung were noted." (PMID 36894556, 2023). "Nevertheless, it is worth mentioning that all the patients exhibiting major tumor regression displayed SMAD4-positive tumors." (PMID 37568581, 2023). "The activated TβRI can specifically recognize downstream Smad2 and Smad3, bind to and activate them, and the activated Smad2 and Smad3 dissociate from TβRI and then form heterologous complex with tumour suppressor gene Smad4." (PMID 37431884, 2023). "To address the question of AMD3100-induced alterations on the tumor stroma, and more specifically on tumor vasculature, we implanted Pten/Smad4-null cells into either prostate or tibia in FVB mice." (PMID 36831366, 2023). "In this study, we verified the binding of miR‐558 to Smad4 using RNA‐binding protein immunoprecipitation assay, and Smad4 exerted a tumour suppressor role in cancer." (PMID 37563869, 2023). "Activin type 1 or TGFBR1 phosphorylates it, subsequently recruits SMAD4 and transmits signals to the nucleus, and is thought to suppress tumor development." (PMID 37509254, 2023). "Altogether, we noted a decrease in proliferation, clonogenecity and migration as supportive of the known tumor suppressor effects of Smad4 in CRC3–7." (PMID 36894556, 2023). "RNA-Seq analysis reveals that SMAD4 expression in the invasive tumor organoids resulted in an immediate transcriptional shift in genes associated with the extracellular environment—both in 3D and 2D cultures." (PMID 38136364, 2023). "In summary, the decrease or loss of CDH1 (E-cadherin gene), SMAD4, PTEN, and FAT1 expression leads to an aggressive tumor with an increased invasive phenotype and increased metastatic potential." (PMID 37687058, 2023). "Our study expands the substrate scope of BCR-ABL1 to the tumor suppressor Smad4, and thus adds another layer of complexity to Imatinib effects." (PMID 36959211, 2023). "This is consistent with studies in other PDAC-derived tumor cell lines, in which SMAD4 acted as an inhibitor of migration or invasion confirming the tumor suppressing function of SMAD4 in PDAC cells." (PMID 37568607, 2023). "The re-expression of SMAD4 in invasive organoids shows a direct impact of SMAD4 in suppressing invasion, though the proliferation in organoids remained intact, suggesting a tumor-suppressive role of SMAD4 beyond just WNT-antagonism." (PMID 38136364, 2023). "Canonical TGFβ/SMAD4 signaling behaves like a tumor suppressor pathway in early stages of tumorigenesis in most tissues." (PMID 37377893, 2023). "By discovering an antagonistic relationship between the tumor suppressors Prdm16 and Smad4 in PDAC, this study paves the way for innovative frameworks with potential therapeutic implications." (PMID 36828547, 2023).
tumor (continued). "The proposed pathway is that SMAD4’s involvement in TGF-β signalling is shared with TGFBR1/2 and FBN1, genes involved in connective tissue disorders, where SMAD4 is a transcriptional regulator and tumour suppressor." (PMID 38066625, 2023). "Similar to the results at the cellular level, here we found that mRNA nano-lantern promoted the expression of Smad4 protein in tumor tissues and induced the decline of MYC, VEGFC, and CXCL5." (PMID 36894556, 2023). "The tumor suppressive properties of Smad4 mRNA nano-lantern on CRC cell lines including effects on proliferation, clonogenicity and migration were then investigated." (PMID 36894556, 2023). "For instance, SMAD4 has a well-documented role in altering the tumor microenvironment to promote metastasis." (PMID 38136364, 2023). "This range likely represents inherent differences in study populations, where rates of SMAD4 alterations increase with greater tumor burden." (PMID 38002058, 2023). "Infiltration of CD8 + cytotoxic T cells paralleled SMAD4 expression in both the tumor and peritumor; the results were more apparent in the tumor tissues." (PMID 37035326, 2023). "Smad4 acts as a tumor suppressor and inhibits the proliferation of tumor cells via Smad4/R-Smad complex." (PMID 37580768, 2023). "SMAD4 (SMAD Family Member 4) is a tumor suppressor that is downregulated through gastric tumorigenesis." (PMID 37386429, 2023). "In CRC, the deletion of SMAD4 in cancer cells resulted in a decrease in S100A8+ monocytes in the tumor microenvironment." (PMID 37190048, 2023). "pINDUCER-SMAD4 Smad4KO BRAFV600E/+ tumor organoids were treated with either vehicle (n = 4) or dox (n = 2) to induce expression of SMAD4 for 48 h and then collected for RNA-Seq." (PMID 38136364, 2023). "Consistent with the in vitro results, SMAD4 restoration resulted in a significant decrease in tumor volumes in vivo and this positively correlated with SMAD4-expression levels." (PMID 37377893, 2023). "Independent pINDUCER-SMAD4 Smad4KO BRAFV600/+ tumor organoid lines were selected using puromycin (2 μg/mL), passaged, and treated for 48 h with doxycycline (dox, 4 μg/mL) to induce SMAD4 expression." (PMID 38136364, 2023). "Our results are generally consistent with previous reports, suggesting that SMAD3 and SMAD4 can act as tumor suppressor genes of CRC and influence patient immune status." (PMID 36969909, 2023). "Smad4 deletion in CKS also enables studies of Smad4 and the downstream TGFβ pathway in tumor progression and microenvironment." (PMID 36011011, 2022). "Survival time after recurrence was evaluated according to SMAD4 status at each central lesion and tumor invasion front." (PMID 36088360, 2022). "We found that HPV increases SMAD4 expression is both HPV-positive HNC tumours and cell lines, impairing its degradation which is mediated by the E3 ubiquitin ligase βTRCP1." (PMID 35144669, 2022). "The analysis indicated that six genes (PIK3CA, CDC27, B2M, PTEN, SMAD4, and IL32) were strongly associated with tumor-infiltrating lymphocytes." (PMID 35903675, 2022). "In some non-tumor colorectal tissue samples this transcript was barely detectable (below 0.01%), while in fetal mouse liver it constituted almost total Smad4 mRNA (over 95%)." (PMID 35034624, 2022). "In HT-29 and SW620 cell lines, total SMAD4 expression was significantly decreased in comparison to the average values for human non-tumor tissue 25-fold and 145-fold, respectively." (PMID 35034624, 2022).
tumor (continued). "The relative abundances of this transcript and the transcript SMAD4–202 that also codes for full protein were analyzed in permanent human cell lines, and in a set of tumor and corresponding healthy tissue samples from patients with CRC." (PMID 35034624, 2022). "Though the TGFβ target SMAD4 is deleted in approximately 55% of PDAC tumors, the effects of SMAD4 loss on tumor immunity have yet to be fully explored." (PMID 35155243, 2022). "The protein level of SMAD4 was inversely correlated with autophagy in orthotopic tumour tissue samples." (PMID 35565415, 2022). "In the hypoxic PDAC microenvironment, HIF-2α induces Wnt signaling via β-catenin and SMAD4 and increases tumor progression." (PMID 35883598, 2022). "Pancreatic cancers, often driven by mutant KRas and, commonly, genetic loss of SMAD4, have an extraordinarily high content of stromal fibroblasts and ECM interspersed with pockets of thriving tumor cells." (PMID 36382146, 2022). "PD-L1 status was closely related to tumor-infiltrating lymphocytes, particularly IFNγ-producing T-cells, which were more abundant in SMAD4-expressing tumors." (PMID 35155243, 2022). "We thought that this intra-tumoral heterogeneity of functional SMAD4 was induced by tumor progression and the effect of SMAD4 on tumor progression depends on tumor stage." (PMID 36088360, 2022). "For example, in patient #1, we found that only a fraction of the cancer cells in vivo had SMAD4 deletions, but essentially all tumor tissue-derived organoid cells from this patient had SMAD4 deletions which were further verified by Sanger sequencing." (PMID 35484598, 2022). "By contrast, β2M and MHC‐I levels were dramatically upregulated in PDAC cells after Smad4 was knocked out and the tumor became sensitive to the host immune control of tumor growth." (PMID 35064757, 2022). "In particular, published TCGA data analysis showed decreased expression of SMAD4 mRNA expression in HPV-negative compared to HPV-positive HNC tumours." (PMID 35144669, 2022). "Together, loss of SMAD4 protein expression in human PDACs correlated with increased levels of STING expression and T cell infiltration in the tumor microenvironment by IHC staining." (PMID 35064757, 2022). "Together, these data suggest that in vivo tumor inhibition by Smad4 deletion requires T cell‐mediated adaptive immune responses." (PMID 35064757, 2022). "To further verify that this is a tumor‐intrinsic Smad4 function, we restored Smad4 expression in Smad4KO cells." (PMID 35064757, 2022). "qRT-PCR and Western blot results exhibited abundant expression of miR-642b-3p and Smad7 yet poor expression of CSMD1 and Smad4 in the tumor tissue of mice treated with miR-642b-3p mimic, the effects of which were undermined by CSMD1." (PMID 35412956, 2022). "In a mouse model of colorectal carcinogenesis in vivo, BRAF V600E mutations in intestinal stem cells promote differentiation and require inactivation of SMAD4 or of intestinal differentiation transcription factor CDX2 for efficient tumor formation." (PMID 36079062, 2022).
tumor (continued). "Using PANC-1 cells as a model of SMAD4-intact PDAC and both BxPC-3 and AsPC-1 cells as a model of SMAD4-deficient PDAC, we next incubated tumor cells with 10ng/mL recombinant TGFβ1 for 24 hours and evaluated the expression of PD-L1 by western blot." (PMID 35155243, 2022). "The expression of SMAD4 was depleted in all tumor tissues, with very weak staining observed in organoid C-TO, E-TO, and F-TO samples." (PMID 35853873, 2022). "Kaempferol and TGF-β receptor (ALK5) binding inhibits the phosphorylation and translocation of Smad2 and reduces the expression of Smad4, thus inhibiting the proliferation, migration, and invasion of tumor cells." (PMID 36147444, 2022). "In glioma cancer, Smad4 protein was differentially expressed in different pathological samples, which further confirmed the key role of Smad4 in tumor invasion and metastasis." (PMID 35251569, 2022). "SPTBN1 is a TGF-β signal-transducing adapter protein which is necessary for Smad3/Smad4 complex formation and functions as a tumor suppressor in many cancers." (PMID 35641855, 2022). "Ablation of SMAD4 in tumor cells altered the immune TME and sensitized tumors to combination immunotherapy." (PMID 35903675, 2022). "Smad4 deficiency induces DNA damage and augments STING‐mediated IFN‐I signaling activation in tumor cells." (PMID 35064757, 2022). "In this study, the experimental results showed that the ability of VPA to inhibit tumor invasion and metastasis at different doses was dose-dependent and was accompanied by changes in the expression of Smad4 protein and EMT parameters." (PMID 35251569, 2022). "We previously visualized more nuclear transitioning functional SMAD4 at the tumor invasion front than the central lesion." (PMID 36088360, 2022). "Specifically, we compared a CRC tumoroid line derived from a SMAD4 wild‐type tumor to a CRC tumoroid line derived from a SMAD4 mutant tumor identified by MSK‐IMPACT sequencing." (PMID 34114372, 2022). "Here, we report that HPV-positive HNC cell lines and tumours show increased expression of SMAD4 compared to the HPV-negative ones." (PMID 35144669, 2022). "Nuclear SMAD4 staining was present in 68% of the tumours, and cytoplasmic SMAD4 staining in 87% of the tumours." (PMID 35756604, 2022). "Concurrently, SMAD4 back TET2 levels in the classical PDAC subtype, and loss of SMAD4 expression displayed reduced 5hmC and GATA6 resulting in a more squamous-like tumor." (PMID 35158814, 2022). "Given the limitations of using bulk tumor mRNA sequencing data from publicly available datasets, we next explored the relationship between SMAD4 expression and tumor immunogenicity in 36 human PDAC excisional biopsies." (PMID 35155243, 2022). "Overall, our findings suggest that the poorly antigenic tumor cells of PDAC are resistant to immune control but deletion of Smad4 increases MHC‐I expression on PDAC cells and promotes antitumor immune response." (PMID 35064757, 2022). "According to the targeted NGS analysis of tumor samples with pre- and post-cetuximab treatment, the copy number of the SMAD4 gene changed, while the TGF-β signaling pathway had various recurrent mutations." (PMID 36430910, 2022). "Another study has been shown that miR-146b-5p was involved in tumor cell migration through SMAD4 targeting in PTC." (PMID 35659780, 2022). "Studies have shown that loss of SMAD4 promotes TGF-β-mediated tumorigenesis by abrogating the tumor-suppressive functions of TGF-β, such as cell cycle arrest, while maintaining the tumor-promoting functions of TGF-β, such as epithelial–mesenchymal transition." (PMID 35892903, 2022). "Some studies have reported that Smad4 protein can act as an independent prognostic factor, and the expression of Smad4 in the nucleus is strongly correlated with tumor size, nuclear grade, pTNM, and tumor invasion progression." (PMID 35251569, 2022).